MIR124-2 (microRNA 124-2)
Synonyms: hsa-mir-124a-2; hsa-mir-124-2; MIRN124-2; MIRN124A2; mir-124-2
Gene: MicroRNA gene on chromosome 8 (64,379,149 to 64,379,257, forward strand). Ensembl gene ENSG00000207816.
Gene Ontology:
Biological process: miRNA-mediated post-transcriptional gene silencing
Cellular component: RISC complex
Homologues: Orthologues: chimpanzee ptr-mir-124a (100% identical), macaque mml-mir-124a-1 (98% identical), mouse Mir124a-2 (98% identical), rat Mir124-2 (98% identical), guinea pig MIR124-2 (86% identical), pig ssc-mir-124a-1 (81% identical), zebrafish mir124-3 (77% identical), tropical clawed frog xtr-mir-124 (72% identical), rabbit MIR124-2 (70% identical), zebrafish mir124-2 (63% identical). Paralogues in human: MIR124-3 (67% identical), MIR124-1 (66% identical).
Diseases named in the same sentence as MIR124-2 in open-access papers:
MIR124-2 is named in the same sentence as 3 diseases in open-access papers, as found by Europe PMC text mining. Sharing a sentence is not in itself a finding about the gene and the disease. The quoted sentences say what the papers report.
breast carcinoma (1 paper, 2022). "We have found that the high expression of MIR124-2 correlates to better relapse-free survival (RFS) of breast cancer patients (p = 0.00004." (PMID 35058523, 2022). "MIR124-2 has previously been reported as an epigenetically dysregulated gene in cancer, however, its role in breast cancer metasetases has not been reported previously." (PMID 35058523, 2022).
breast tumours (1 paper, 2022). "This suggests that RP11-713P17.4 and NUS1P3 are frequently methylated in BBM but not in BP, and MIR124-2 methylation frequency is enriched BBM compared to primary breast tumours." (PMID 35058523, 2022).
tumor (1 paper, 2025). "Mir124‐2, on the other hand, does already have a clearly defined role as a tumor suppressor, which manifests through the inhibition of proliferation, aggressiveness, apoptosis, and invasion of tumor cells." (PMID 40556436, 2025).